NGF (nerve growth factor)
Diseases named in the same sentence as NGF in open-access papers (continued):
Sharing a sentence is not in itself a finding about the gene and the disease.
COVID-19 (continued). "However, NGF was elevated compared with BDNF in the exposed COVID-19 group." (PMID 33917718, 2021). "Both NGF and GDNF levels were significantly lower in COVID-19 patients at admission compared with healthy individuals." (PMID 41714345, 2026). "In this context, NGF and BDNF come into play as mediators known to be dysregulated in conditions of severe COVID-19, where an impairment of the central nervous system was documented." (PMID 39596862, 2024). "In this sense, the relationship between NGF and BDNF and COVID-19 passes through an interventional strategy (physical exercise) aimed at restoring the physiological balance of the BDNF system." (PMID 39596862, 2024). "NGF and BDNF values in acute and remission phases of COVID-19 patients were first compared with those assessed in the six controls." (PMID 36579579, 2022). "Overall, the findings described herein highlight the importance of NGF and BDNF as dynamic biomarkers for monitoring disease and reinforces the possibility of using saliva and sera for quick, non-invasive COVID-19 screening." (PMID 36579579, 2022). "In a case report, Petrella and coworkers introduced the possibility to use serum NGF and BDNF as new predictive biomarkers of COVID-19’s long-term effects, especially in girls." (PMID 36579579, 2022). "This study aims to evaluate the levels of circulating and salivary NGF and BDNF in COVID-19 patients, comparing their expression between acute and remission phases of disease." (PMID 36579579, 2022). "This decline in NGF and BDNF may lead to outcomes such as fatigue, memory impairments, and cognitive failure, outcomes now normally observed in some long-COVID-19 individuals or in the post-acute actions of SARS-CoV-2 exposure." (PMID 39596862, 2024). "However, another investigation revealed increased NGF and BDNF in saliva and serum during the acute COVID-19 phase, but reduced levels were observed 6 months after the acute phase." (PMID 36831321, 2023). "We predicted that NGF and/or BDNF could be used as early biomarkers of COVID-19 morbidity in adolescents." (PMID 35626317, 2022). "Our study was devoted to the quantification of NGF and BDNF in COVID-19 patients, their transition from acute to remission phases, and the possibility to identify in this expression some predictors for the remission and course of COVID-19." (PMID 36579579, 2022). "the alteration of circulating or salivary NGF and BDNF levels in COVID-19 patients." (PMID 36579579, 2022). "BDNF did not correlate with NGF in the COVID-19 PCR group (p = 0.75) or in the viral symptoms group (p = 0.26)." (PMID 33917718, 2021). "NGF and BDNF concentrations were comparable in the COVID-19 PCR and viral symptoms groups." (PMID 33917718, 2021). "We observed that BDNF and NGF concentrations were comparable in COVID-19 PCR, viral symptoms suggestive of COVID-19, mastitis, and no mastitis groups." (PMID 33917718, 2021). "They assumed that the etiology is a cross-reaction between the COVID-19 viral peak protein and antigens on the surface of the microtextured implants or related to excess production and secretion of brain-derived neurotrophic factor (BDNF) and nerve growth factor (NGF)." (PMID 39712691, 2024). "Though the relationships between NGF and COVID-19 have been not described thus far, NGF may also be a potential therapeutic target for COVID-19 because NGF is an emerging target in PF." (PMID 34502019, 2021). "BDNF and NGF concentrations were not influenced by the elapsed time from infection to milk collection in mothers with a confirmed COVID-19 PCR and in mothers with viral symptoms suggestive of COVID-19." (PMID 33917718, 2021). "On the other hand, our findings, by showing a high correlation between NGF and BDNF in both matrices, would suggest that at least one test and one parameter, the quick-and-easy one, depending on the situation, might be useful for the prediction and/or prognosis of COVID-19." (PMID 36579579, 2022).
COVID-19 (continued). "We found significant differences due to COVID-19 disease severity for both BDNF and NFL but not for NGF in the ratios with MMP-2 or MMP-9." (PMID 36831321, 2023). "Little is known about the changes in NGF and BDNF in adult COVID-19 patients, and no data are available when shifting from infection (acute) to non-infectious (chronic) SARS-CoV2 disease." (PMID 36579579, 2022). "NGF and BDNF concentrations were not affected by the elapsed time from infection to milk collection in mothers with a confirmed COVID-19 PCR test or in mothers with viral symptoms suggestive of COVID-19." (PMID 33917718, 2021). "We observed that NGF and BDNF concentrations varied between individual mothers in the three groups (COVID-19 PCR, viral symptoms, and unexposed) from non-detectable to 2140 pg/mL for NGF and from non-detectable to 207 ng/mL for BDNF." (PMID 33917718, 2021).
neuritis (15 papers, 2009 to 2025). A neuropathy arising from inflammation of one or more nerves. "It is widely acknowledged that NGF provides trophic support to neurons and promotes neuritis growth." (PMID 39199870, 2024). "NGF is the most frequently investigated neurotrophic factor that promotes neuritis outgrowth in vivo and in vitro." (PMID 35204786, 2022). "Studies have found that NGF can also promote the occurrence and development of neuritis and induce excessive cardiac sympathetic nerve activity, indicating that NGF plays an important role in physiological and pathological conditions." (PMID 34471416, 2021). "NGF can induce the differentiation of PC-12 cells which develop extended neuritis and an increased number of synaptic-like vesicles." (PMID 27626445, 2016). "Stimulating/neutralizing activities were determined by evaluating respectively the promoting (50ng/ml NGF) or blocking (50ng/ml NGF pre-incubated with 500 ng/ml ANA) neuritis outgrowth activity on PC12 cultured over 6 days (6d)." (PMID 25897972, 2015). "Survival (averaged cell number; E) and neuritis outgrowth (length; F) were quantified in three optic field from 20 untreated and NGF treated wells." (PMID 25897972, 2015). "When PC12 cells were treated with a low concentration of pheophytin A 33 (3.9 μg mL−1) in the presence of a low level of nerve growth factor (10 ng mL−1), the compound produced neuritis outgrowth similar to that produced by a high level of nerve growth factor (50 ng mL−1)." (PMID 35517468, 2020). "In presence of NGF, these cells are characterized by enhanced expression of NGF-receptors and rhodopsin, the specific marker of photoreceptor and better cell survival, as well as neuritis outgrowth." (PMID 25897972, 2015). "Previous in vitro toxicity assay on DMSA coated Fe2O3-NPs (5–12 nm) also indicated that exposure at concentrations of 1.5–15 mM resulted in a diminishing viability and capacity of PC12 cells to extend neuritis in response to their putative biological cue, i.e. nerve growth factor." (PMID 22912902, 2012). "During visual system development, NGF, TrkA and p75, as well as other NTs and their related receptors, are highly expressed in numerous visual centers, from the retina to the visual cortex, where NGF influences neuritis outgrowth, survival and selective apoptosis." (PMID 19473529, 2009). "PC12 spherical cells start to develop into neuronal cells following 48 h of treatment with nerve growth factor (NGF), resulting in mature neuritis that reaches the peripheral areas." (PMID 36364649, 2022). "A widespread neuritis outgrowth and an higher number of trkANGFR positive cells was observed upon NGF stimulation (B), as compared to untreated or ANA and/or ANA/NGF treated cells (C-D)." (PMID 25897972, 2015). "The results found here showed a greater tendency for greater expression of NGF in non-co-infected multibacillary forms, considering the occurrence of neuritis, occurrence of reactions, and a greater number of affected nerve trunks, even when compared to co-infected multibacillary forms." (PMID 41156731, 2025). "Higher expression of NGF was observed in non-co-infected multibacillary patients regardless of the occurrence of neuritis (688.38 ± 534.82 labeled cells per square millimeter for patients with neuritis and 689.62 ± 490.71 labeled cells per square millimeter for patients without neuritis)." (PMID 41156731, 2025).
dry eye (14 papers, 2010 to 2025). "In severe dry eye, disturbed corneal sensation together with decreased tear production cause damage to the ocular surface, which can be prevented by NGF application aimed at improving corneal innervation and tear secretion." (PMID 37176566, 2023). "NGF was elevated in tears of contact lens wearers with dry eye, and the levels were associated with a decrease in the nerve plexus density in the cornea, supporting the theory that dry eye results from a decrease in the afferent part of the lacrimal loop." (PMID 26605353, 2014). "Clinical studies involving human participants have also demonstrated a positive correlation between tear NGF levels and dry eye severity." (PMID 40649793, 2025). "The goal of dry eye treatment is to somehow suppress both the elevated NGF levels and the dry eye symptomology in order to reduce the rises in inflammatory parameters (pro-inflammatory cytokine release), resulting from TRPV1 activation." (PMID 40422222, 2025). "Gong Q examined the impact of NGF eye drops on corneal sensitivity, regeneration of corneal nerves, and dry eye symptoms in patients after LASIK surgery compared to patients treated with saline (NS) and lubricating eye drops." (PMID 38203537, 2023). "Some authors observed higher nerve growth factor (NGF) levels in tears in dry eye patients compared to healthy participants." (PMID 37176566, 2023). "Currently, the future of treating conditions with disrupted corneal innervation and dry eye has become the use of recombinant human NGF eye drops." (PMID 38203537, 2023). "NGF concentration is increased in the tears of dry eye patients and is released by fibroblasts and epithelial cells of the cornea and the conjunctiva as well as local immune cells where it promotes cell survival." (PMID 36430547, 2022). "NGF has shown to stimulate mucin secretion in human conjunctival cells and also in a surgically-induced dry eye dog model." (PMID 30805711, 2019). "Tavilermide is a proteolytically stable, cyclic NGF peptidomimetic partial agonist of the TrkA receptor and has been evaluated in a rat model of dry eye." (PMID 30805711, 2019). "NGF can increase ocular surface sensitivity, inhibit inflammatory reactions, reduce the apoptosis of corneal epithelium and regulate tear film production by lacrimal gland and goblet cells, thus NGF can be considered a novel treatment for dry eye." (PMID 28661456, 2017). "The tear nerve growth factor (NGF) levels were higher in dry eye patients compared to age- and gender-matched healthy control participants." (PMID 26605353, 2014). "In another study, tear levels of NGF were increased in dry eye patients whereas related peptides: Calcitonic Gene Related Peptide (CGRP) and Neuropeptide (NP) Y concentrations were decreased compared to healthy participants." (PMID 26605353, 2014). "In these patients, prednisolone treatment for 28 days resulted in a decrease in tear NGF levels, which occurred together with clinical improvement of dry eyes." (PMID 26605353, 2014). "Further studies are required to determine why the NGF levels are elevated in dry eye, and perhaps the use of NGF as a biomarker should be delayed until substantial longitudinal studies of NGF levels are available." (PMID 26605353, 2014). "The NGF mimetic was able to induce an improvement of dry eye test parameters and glycoprotein secretion." (PMID 26605353, 2014). "Topical NGF treatment was indicated to induce an increase in goblet cell density in an animal model of dry eye." (PMID 21179428, 2010). "Additionally, tear NGF levels are also elevated in patients suffering from keratoconjunctivitis sicca, which can be reduced by 0.1% prednisolone treatment." (PMID 40422222, 2025). "Moreover, they found a direct correlation between NGF tear levels and the severity of dry eye (p = 0.009)." (PMID 37176566, 2023). "Promotion of wound healing and reinnervation by NGF in dry eye is now described." (PMID 36430547, 2022).
dry eye (continued). "In dogs with dry eye, NGF treatment increased tear production and goblet cell density." (PMID 36430547, 2022). "Topical administration of NGF was successively applied in corneal healing, neurotrophic keratitis, immune corneal ulcer, dry eye syndrome, corneal transplantation, and diabetic cornea, highlighting the therapeutic potential of NGF in treating corneal diseases with a strong immune component involved." (PMID 31889912, 2019). "Furthermore, the level of tear NGF was correlated with clinical severity of dry eye while CGRP and NPY levels were inversely correlated to these clinical parameters." (PMID 26605353, 2014). "Meanwhile, studies of conjunctival goblet cells have shown that NGF can stimulate mucin secretion, topical application of NGF can increase the number of goblet cells in dogs affected by surgical dry eye, and NGF receptors can be expressed by conjunctival and corneal epithelial cells." (PMID 21179428, 2010). "The dry eye marker MMP-9, cytokines (IL-1β, IL-8), and pain markers (NGF, CGRP) were quantified in tear samples with immunoassays." (PMID 35886858, 2022). "Previously, it has already been demonstrated that NGF could inhibit oxidative injury that was induced by hyperosmotic stress or high glucose levels indicating the remarkable capacity of NGF on scavenging ROS generated during the pathogenesis of dry eye or diabetic cornea." (PMID 31889912, 2019). "Similar to NGF, tavilermide stimulated glycoprotein production in conjunctival cultures, increased phosphorylation of MAPK leading to activation in vitro, and improved corneal staining in an experimental dry eye model in mice." (PMID 36430547, 2022). "In addition to NGF, the calcitonin gene-related peptide (CGRP) is also an interesting starting point, as it appears to be involved in corneal nociception and dry eye symptoms." (PMID 35886858, 2022). "Indeed, the ocular surface status in dry eye is affected by the pro-inflammatory mediators such as IL-1, IL-6, TGF-β, TNF-α, and MMP-9; neurotrophic factors such as NGF; and antigen-presenting cells." (PMID 32698387, 2020).
sarcoma (14 papers, 2008 to 2025). A usually aggressive malignant neoplasm of the soft tissue or bone. "Ligand-directed strategies are conceptually attractive but require careful risk assessment: anti-NGF monoclonal antibodies demonstrate on-mechanism analgesia yet carry joint-specific toxicities that are relevant to sarcoma populations with musculoskeletal comorbidities." (PMID 41567220, 2025). "NGF/TrkA signaling is increasingly implicated in sarcoma biology." (PMID 41567220, 2025). "Rita Levi-Montalcini's 1953 discovery of nerve growth factor (NGF) in mouse sarcoma tumors marked a groundbreaking moment in neuroscience." (PMID 40153582, 2024). "The Nerve Growth Factor (NGF) was discovered by R. Levi-Montalcini nearly 60 years ago after the transplantation of a malignant mouse sarcoma into the body wall of a 3-day-old chick embryo." (PMID 27439311, 2016). "She identified NGF as a substance secreted from mouse sarcoma tissue that stimulated neuronal survival and neurite outgrowth from chicken ganglia." (PMID 24212627, 2011). "Sarcoma cells have been known for almost 50 years to produce and secrete NGF, and in fact, the molecule was originally discovered in experiments with sarcoma cells." (PMID 18312658, 2008). "TrkA expression and NGF-mediated signaling were then studied in human sarcoma cell lines." (PMID 41301953, 2025). "However, it is pertinent here to remember that NGF was first shown to be secreted from mouse sarcoma tissue and that neurotrophins are expressed in many areas of the body and frequently participate in signaling beyond the nervous system." (PMID 24212627, 2011). "NGF reduces apoptosis induced by chemotherapeutics in sarcoma cells." (PMID 18959781, 2008). "Nerve growth factor (NGF) was the first neurotrophin discovered in the 1950s by Rita Levi-Montalcini and Viktor Hamburger in mouse sarcoma cultures in vitro." (PMID 28273811, 2017). "The relevance of neurotrophins to tumor biology is not well-characterized, although there are clear links: NGF was originally purified from a sarcoma, TrkA was discovered in a human colon carcinoma biopsy and p75NTR was purified from a human melanoma cell line." (PMID 24212627, 2011).
brain injury (13 papers, 2014 to 2026). Acute and chronic (see also brain INJURIES, CHRONIC) injuries to the brain, including the cerebral hemispheres, CEREBELLUM, and brain STEM. "Eligible studies involved pediatric brain injury patients receiving NGF, with outcomes via clinical scales, imaging, or EEG." (PMID 42075845, 2026). "On the contrary, an inverse correlation between NGF levels and symptom severity (as assessed by Glasgow Coma Scale score) has been reported in human children with traumatic brain injury." (PMID 36136675, 2022). "The beneficial action of NGF enhancement by pretreatment with SB was reported in other brain injuries." (PMID 30767185, 2019). "We decided to analyse the effect of brain trauma and galectin-3 gene deletion on the mRNA levels of NGF and BDNF." (PMID 28128358, 2017). "In the aftermath of TBI, NGF orchestrates neuroprotective mechanisms, promotes neuronal survival, and facilitates neural repair processes, thus serving as a potential therapeutic target for mitigating the adverse sequelae of pediatric brain trauma." (PMID 39056738, 2024). "In the context of traumatic brain injury (TBI), NGF levels increase in response to the damage, facilitating neuronal regeneration and reducing the extent of brain injury." (PMID 39056738, 2024).